TFPI2 (tissue factor pathway inhibitor 2)
Diseases named in the same sentence as TFPI2 in open-access papers (continued):
Sharing a sentence is not in itself a finding about the gene and the disease.
cancer (continued). "Similar to cancer cells, several literatures suggest that aberrant expression of TFPI2 suppresses trophoblast cell proliferation and invasion and promotes cell apoptosis; however, TFPI1 has an effect opposite to TFPI2 on the trophoblast invasion." (PMID 37238908, 2023). "In some highly aggressive cancers, deletion of the TFPI-2 gene locus on chromosome 7q results in the complete lack of TFPI-2 protein expression." (PMID 33947134, 2021). "For example, at this point we do not know how cancer cells initiate downregulation of TFPI2 by miRNAs in CAFs, or what kind of promoters or other upstream signals are responsible for the upregulation of miR-23a." (PMID 32559232, 2020). "By contrast, in other cancers, expression of TFPI2 is reduced or absent following aberrant methylation of its promoter region." (PMID 27798689, 2016). "It is possible that the origin of TFPI2 was not the cancer cells in these patients." (PMID 34009487, 2021). "Bikunin, TFPI-2 and SPINT2 are Kunitz proteins with anti-cancer effects, and as potent protease inhibitors, the EgKI proteins may also exhibit similar properties which can be exploited in cancer therapy." (PMID 26645974, 2015). "Downregulation of TFPI-2 was also found in a third patient (patient 4) without any detectable LCT13 and TFPI-2as expression, a finding likely to reflect multiple mechanisms leading to loss of expression of this gene in cancer." (PMID 23703216, 2013). "Therefore, this cancer cell–specific transcript initiates at an L1-ASP and extends uninterrupted over more than 300 kb across the genomic locus to generate a large RNA antisense to TFPI-2." (PMID 23703216, 2013). "We further demonstrated that in up to 50% of colorectal cancers lacking expression of the tumor suppressor gene TFPI-2, this silencing is associated with the presence of the overlapping anti-sense LCT13 transcript, suggesting that its expression may have a functional consequence in cancer." (PMID 28300471, 2017). "Although TFPI2 is responsible for the ATRA-mediated inhibition of HuH7 cell invasion, ATRA also suppressed HepG2 cell invasion without inducing TFPI2, which suggested that ATRA employs several mechanisms to suppress cancer invasion in the context of cell lines." (PMID 29757260, 2018). "In many cancer cells, the hypermethylation of the TFPI-2 promoter does not appear to be the sole basis for TFPI-2 gene silencing, as one or more components of the cellular transcription machinery that regulates TFPI-2 expression may also be hypermethylated leading to their silencing as well." (PMID 17352822, 2007).
infection (7 papers, 2012 to 2024). The state of being infected such as from the introduction of a foreign agent such as serum, vaccine, antigenic substance or organism. "We previously demonstrated that higher levels of the tetrad heparanase, TF, TFPI, and TFPI-2 are present in hypercoagulable states as malignancy, recurrent abortions, pregnancy, and infection, mainly in the tissues’ microcirculation." (PMID 39766213, 2024). "In experimental murine models of infection and endotoxin challenge, we show that TFPI-2 is up-regulated in several organs, including the lung." (PMID 30254643, 2018). "Within the locus we also identified host genes whose expression increased (Samd9l, Asns, Gpr85, and Tfpi2) or decreased (Pon1, Hepacam2, Tmem106b, and Pppr9a1) 2-fold (P < 0.05) 72 hours after infection with H5N1 IAV in D2, B6 or both mouse strains." (PMID 25418976, 2014). "The expression of Tfpi2 was significantly higher only after infection in the trigeminal ganglia (2 dpi) and the brain stem (4 dpi) in DA rats compared to PVG rats." (PMID 22761571, 2012). "To evaluate if the full-length protein of TFPI-2, in addition to limit bacterial infiltration, exerts host defense properties by keeping inflammation at bay during infection we measured inflammatory cytokine levels in both BALF and citrate plasma after 12 h post-infection." (PMID 30254643, 2018). "We therefore hypothesized that TFPI-2 C-terminal derived peptides may have an important function in the host defense to infection, thus they may be interesting agents for drug development." (PMID 27349742, 2016). "In a broader perspective, a picture thus emerges; suggesting that C-terminal fragments from both TFPI-1 and TFPI-2 may be released during inflammation and infection, serving as modulators of both antimicrobial activity and coagulation." (PMID 27349742, 2016). "The protective effect of mouse VKG24 in infections caused by Gram-negative pathogens may also apply to other vertebrate TFPI-2 C-terminal peptides." (PMID 27349742, 2016). "At every 24 hours within 4 days after lentiviruses infection of SiHa and CaSki, we used Q-PCR to analyze the expression of E6, E7, DNA methyltransferase genes (DNMT1, DNMT3A, DNMT3B and DNMT3L), and tumor suppressor genes (MT1G, NMES1, RRAD, SFRP1, SPARC and TFPI2)." (PMID 26329329, 2015). "On a systemic level (plasma) 12 h post-infection IL-6, IL-10, and MCP-1 was higher in TFPI-2−/− mice and no significant changes were observed in INF-γ, TNFα, and IL-12p70, whereas in BALF fluid, IL-10, and MCP-1 was higher in TFPI-2−/− mice." (PMID 30254643, 2018).
bacterial infection (1 paper, 2012). "The identification of TFPI-2 in skin, as well as in wounds, is therefore well in line with previous observations, and extend these into a setting of skin wounding and bacterial infection." (PMID 23300768, 2012). "Furthermore, the present data do not disclose whether TFPI-2 confers protection to bacterial infection in vivo." (PMID 23300768, 2012).
digestive system cancer (1 paper, 2026). A primary or metastatic malignant neoplasm involving any part of the digestive system. "Notably, the SDC2 marker displayed zero false positives among 98 digestive system cancer cases within the control groups, while SFRP2 and TFPI2 showed 8.16% and 10.2% false-positive rates, respectively." (PMID 41695361, 2026).
TFPI2 also shares sentences with these, for which no sentence is quoted: adenocarcinoma (3 papers); colorectal adenoma (3); oral squamous cell carcinoma (3); pancreatic ductal adenocarcinoma (2); renal fibrosis (2); uterine fibroids (2); acute coronary syndrome (1); asthma (1); bladder tumors (1); cardiovascular diseases (1); cholangiocarcinoma (1); COVID-19 (1); dysplasia (1); endothelial dysfunction (1); esophageal squamous cell carcinoma (1); Ewing sarcoma (1); gallbladder cancer (1); gram-negative bacterial infections (1); gynecological disease (1); Insulin resistance (1); intraductal papillary mucinous neoplasms (1); kidney stones (1); laryngeal carcinoma (1); lung adenocarcinoma (1); mesothelioma (1); Obesity (1); oesophagus (1); osteosarcoma (1); pregnancy-induced hypertension (1); pulmonary embolism (1).
A further 7 diseases each share a sentence with TFPI2 in 1 paper.